AHR (aryl hydrocarbon receptor)
Diseases named in the same sentence as AHR in open-access papers (continued):
Sharing a sentence is not in itself a finding about the gene and the disease.
cancer (continued). "It should also be noted that the kynurenine activation of the AhR will actively suppress natural killer cells, and therefore the capacity of the body to detect and eliminate virus-infected cells as well as cancer cells." (PMID 36211365, 2022). "Epidemiological cohorts exposed to dioxins have also been studied to understand sustained AhR-dependent activation and elevated cancer incidence, morbidity, and/or mortality within exposed populations, producing variable results." (PMID 35626744, 2022). "Depletion of Trp and Trp-Kyn-AHR-related metabolism results in cancer immunity evasion, which shares consistency with our study." (PMID 36035152, 2022). "These pathways are known to be involved in RB tumorigenesis and contribute to upregulation of aryl hydrocarbon receptor (AhR) signaling, estrogen-mediated S-phase entry for cancer cell proliferation, and others." (PMID 36130950, 2022). "Intriguingly, UCHL3, as a member of UCH family, has recently been revealed to be highly expressed in NSCLC, maintaining the cancer stem-like properties through stabilizing the aryl hydrocarbon receptor (AhR) for γ-H2ax." (PMID 35918714, 2022). "A correlation between the AhR expression and cancer initiation and its potential use as a therapeutic target has been explained by several researchers in breast, glioblastoma, gastric, and lymphoma, colon, and melanoma." (PMID 35742838, 2022). "This research investigated the immunotherapeutic value of AhR in 33 human cancers, providing evidence regarding the function of AhR and its role in clinical treatment." (PMID 34290693, 2021). "Later studies showed that AHR plays an important role in the occurrence and development of various types of cancer." (PMID 34784845, 2021). "Although we are limited by a small sample size (n = 21), this is a unique study exploring different endurance training modalities on NK cell activation via AhR/IDO axis in cancer patients." (PMID 34477931, 2021). "They interacted with transcription factor receptors, such as aryl hydrocarbon receptor, then promoted the transcriptional expression of glycolytic key enzymes, such as hexokinase 2 or pyruvate kinase M2, facilitated cancer cells progression." (PMID 35083240, 2021). "Recently, there is increasing attention on AhR as an attractive target in cancer, immunology, inflammatory bowel diseases, and aging." (PMID 33923487, 2021). "In contrast to cancer cells, we demonstrated that AhR was negligibly expressed in hiPSCs, and its inhibition did not affect cell survival and proliferation, highlighting a distinct signaling property of hPSCs." (PMID 33615198, 2021). "AHR targets change with cell, tissues, and ligands for the context specificity which hinders pan-cancer analysis of AHR activity." (PMID 33692337, 2021). "In this way, AHR is involved in cancer cell-mediated immunosuppression, PD-1 up-regulation in CD8+ T cells, and resistance to immune checkpoint inhibitors in different IDO-1 overexpressing cancer types." (PMID 34559251, 2021). "I3P is responsible for AhR activation, that favors cancer cell motility and immune response suppression." (PMID 34068423, 2021). "Historically identified as a sensor of xenobiotics and mainly toxic substances, AhR has recently become an emerging pharmacological target in cancer, immunology, inflammatory conditions, and aging." (PMID 33923487, 2021). "In the clinical significance of IL4I1, the authors found that IL4I1 expression and AHR activity were enhanced in primary cancer tissues and were higher in metastatic melanoma compared to primary melanoma." (PMID 33692337, 2021). "Kyn is an endogenous ligand for aryl hydrocarbon receptor (AhR) that affects the biology of immune cells and cancer cells." (PMID 34163018, 2021). "The crosstalk between OCT4 and AhR has been also suggested from studies using stem-like cancer cells that, in fact, proposed a reciprocal suppression between AhR and such a pluripotency factor." (PMID 34478649, 2021).
cancer (continued). "Kynurenines are ligands for arylhydrocarbon receptor (AhR) ligands to promote cell migration and immune tolerance, thereby driving cancer progression." (PMID 34568308, 2021). "Here, we have proposed several therapeutic strategies for the treatment of cancer in the context of precision medicine that can be applied by considering the level and activity of the AhR transcription factor." (PMID 33451095, 2021). "This is of clinical relevance as promising cancer therapeutics based on the intervention of the AhR/IDO axis are already under extensive investigation." (PMID 34477931, 2021). "Another possible strategy is to consider the level of AhR expression and that of its activity (expression of correlated genes) as a surrogate marker for new putative cancer therapies." (PMID 33451095, 2021). "Here, we summarize the role of AhR in cancer mechanisms, based on previous studies and the analysis of a set of genetic and genomic databases." (PMID 33451095, 2021). "It was also reported that TRP derivatives negatively regulate cancer cell stemness via AhR signaling, reducing tumorigenicity." (PMID 33615198, 2021). "Results from experiments in mice that overexpress a constitutively active AhR showed that these animals are more prone to develop cancers." (PMID 34746229, 2021). "Tryptophan derivatives and the AhR signalling pathway regulate the transcription of Oct4 and cancer cell stemness, opening a new therapeutic avenue to target stem-like cancer cells." (PMID 33453053, 2021). "The exogenous AhR activator, 5F 203 (2-(4-amino-3-methylphenyl)-5-fluorobenzothiazole), has shown a positive effect in several cancers." (PMID 33451095, 2021). "Alternative AhR-targeting strategies can also be considered, such as AhR as a complementary target to increase the efficiency of cancer therapy or a means to counteract resistance mechanisms." (PMID 33451095, 2021). "Previous studies have reported the potential of aryl hydrocarbon receptor (AhR) in cancer immunotherapy." (PMID 34290693, 2021). "Here it needs to be emphasized that, like enzymes, AhR activation can have a direct effect on cancer cells or contributes to immunosuppressive microenvironment development." (PMID 34071442, 2021). "Considering the robust correlation between AhR and PRAD, UVM, TGCT, PCPG, and UCS, GSEA was performed to investigate the potential pathways involved in AhR signaling in these cancers." (PMID 34290693, 2021). "AhR functions as a pro-tumoral factor by directly modulating the invasive properties of cancer cells." (PMID 33451095, 2021). "Activation of AhR is now known to be involved in the pathogenesis of several diseases, such as cancer, cardiovascular diseases, inflammatory diseases, atherosclerosis, and neurodegenerative disease." (PMID 34502168, 2021). "Based on the results that IL4I1 develops a metabolic resistance mechanism against ICB and/or IDO1 by activating AHR, this research provided a new and crucial avenue for cancer therapy." (PMID 33692337, 2021). "In contrast, Trp metabolites, including indoles, can activate intestinal AhR to suppress colonic stem and progenitor cell growth and reduce tumorigenesis in vivo; potentially ameliorating cancer stem cell proliferation." (PMID 33916690, 2021). "To date, only two phase 1 clinical trials have been initiated to test direct modulation of AhR in cancer." (PMID 33451095, 2021). "Kynurenine activates the transcription factor aryl hydrocarbon receptor (AhR) which induces immunosuppression by disrupting the ability of dendritic cells and T cells to eliminate cancer cells." (PMID 33661419, 2021). "Aside from cancer cells, immune B cells require functional AhR to optimally proliferate, through activation of cyclin O." (PMID 33615198, 2021). "Recent studies revealed multiple roles of AhR in skin physiology and disease, including melanogenesis, inflammation and cancer." (PMID 33499346, 2021).
cancer (continued). "A number of strategies have been investigated in the context of targeting AhR as a first-line treatment for cancer." (PMID 33451095, 2021). "The role of AhR as a sensitizer of existing targeted cancer therapies has thus far been little studied." (PMID 33451095, 2021). "For example, kynurenine (Kyn), a tryptophan metabolite in the dominant kynurenine pathway, was shown to be produced by breast, head and neck, and brain (glioblastoma) cancers at levels sufficient to activate the AHR (e.g., ~90 μM) (black font)." (PMID 33396563, 2020). "The cytokine/IDO/kynurenine/AhR pathway is relevant to a wide array of diverse medical conditions, including neuropsychiatric conditions, as well as all cancers." (PMID 33375613, 2020). "AhR is a transcription factor and activation of AhR of cancer cells by kynurenine increases the expression of genes promoting cell migration." (PMID 33085694, 2020). "On the other hand, environmental contaminants such as TCDD, which act as potent AhR agonists and remain in the system for a very long time, are well characterized for their properties to suppressing the immune response and inducing cancer." (PMID 33348596, 2020). "The AhR suppression of the anti-viral response parallels the immune suppression that is evident across most cancers." (PMID 32867244, 2020). "Recent studies suggest that AhR activation enhances the initiation, promotion, progression, invasion, and metastasis of cancer cells." (PMID 32957545, 2020). "Several chemotherapeutic agents have been shown to induce CYP1B1 in cardiovascular and cancer cells, possibly via activating the Aryl hydrocarbon Receptor (AhR), ROS generation, and inflammatory cytokines." (PMID 33185690, 2020). "The use of AhR ligands is not limited to anti-cancer therapy but given the roles of AhR in the intestines and skin, targeting the AhR is challenging also in the treatment of inflammatory bowel disease (IBD) or skin pathologies." (PMID 32316498, 2020). "Emerging evidence indicates an oncogenic role of AhR in the initiation, promotion, progression, invasiveness, and metastasis of cancer." (PMID 32325928, 2020). "As a result, the identification and characterization of natural molecules that can interact with and modulate AhR activity are expected to be particularly useful for the treatment of cancer." (PMID 32085612, 2020). "Recently, it has been reported that its activation altered innate and adaptive immune responses, but there were also evidence of the involvement of AhR in cancer initiation and metastasis." (PMID 32806665, 2020). "Our studies therefore reveal a novel mechanism whereby AHR activation as well as CYP1 enzymes can impact the progression of cancer." (PMID 32398692, 2020). "Dysregulation of AhR signalling has been involved in many cancer types, but the pro-tumoral or anti-tumoral effect of AhR is largely context-dependent." (PMID 32988402, 2020). "Since only AhR-expressing cancer cells are vulnerable to phortress, patients need to be properly screened to ensure that they will benefit from the drug." (PMID 31998435, 2020). "The ligand-activated transcription factor AhR has been mainly studied so far for its xenobiotic metabolising role in the field of toxicology, but emerging evidence has raised attention to its cancer-related function." (PMID 32988402, 2020). "Increasing evidence reveals that Carbidopa can inhibit cancer cell growth and induce apoptosis through aryl hydrocarbon receptor (AHR) in some cancers." (PMID 32404918, 2020). "Many of the studies, conducted with diverse cancer types, exploited environmental and, more recently, endogenous AHR ligands to untangle the AHR’s role in cancer." (PMID 33396563, 2020). "This, in turn, was unexpected as binding of AHR on the regulatory regions of these genes and modulation of expression has been demonstrated previously in both hESCs as well as cancer stem-like cells." (PMID 33260776, 2020).
cancer (continued). "The development of antitumor therapy by direct inhibition of AhR is in its infancy and requires a more complete understanding of the involvement of AhR in cancer initiation/progression and in the functioning of the immune system." (PMID 32325928, 2020). "Apparently, in different cases, AhR antagonists or agonists can exert either a pro- or antitumor influence, modulating immune responses and acting directly on cancer cells." (PMID 32325928, 2020). "In this study, we found that UCHL3 is a contributing factor to cancer stem-like properties that promotes tumorigenesis by stabilizing AhR protein degradation." (PMID 32546741, 2020). "The cytokine/IDO/kynurenine/AhR pathway is present within cancer cells, with intracellular AhR activation affording protection in cancer cells." (PMID 33375613, 2020). "Higher expression in human cancers of the genes down-regulated by AHR knockout (i.e., those driven by baseline AHR activity) significantly correlated with poorer survival in all eight cancer types." (PMID 33396563, 2020). "Note that a kynurenine concentration sufficient to activate AhR is generated in response to inflammation, and a substantial number of malignant tumors arise from sites of chronic infection and inflammation." (PMID 32325928, 2020). "The AHR plays a role in both innate and adaptive immune responses and is now considered a possible therapeutic target in cancer treatments." (PMID 33348604, 2020). "The Aryl hydrocarbon receptor (AhR) has recently been postulated as a molecular target for cancer treatment." (PMID 32443455, 2020). "There are complex relations among IDO/TDO, kynurenine, and AhR, which are disrupted by the progression of cancer." (PMID 32325928, 2020). "These obeservations suggest the existence of IDO/TDO-mediated activation of the AHR pathway across cancer types." (PMID 32782249, 2020). "Aryl hydrocarbon receptor (AhR) is expected to promote initiation, progression and invasion of cancer cells regulating proliferation, differentiation, gene expression, inflammation, cell motility and migration." (PMID 31936153, 2020). "The identification of increased AhR gene expression on tumors and increase of endogenous ligands has led to the research of AhR antagonists, like flavonoids, in the treatment of cancer." (PMID 32957545, 2020). "Plasma levels of the AhR agonists kynurenine and indoxyl sulfate increased in mice bearing cancer cell xenografts." (PMID 32932962, 2020). "Given that Line-1 and other retrotransposon elements mobilize throughout the mammalian genome and damage host DNA via mutational insertions, these results suggest a wide-ranging effect of AHR activation on cancer progression to a highly metastatic state." (PMID 33396563, 2020). "Our results indicate that kynurenine functions as an oncometabolite, at least in part, by activating the transcription factor AHR, which then regulates growth promoting genes in cancer cells." (PMID 31922097, 2020). "The demonstration of chronic AHR activity in a variety of cancers begged the question of what was persistently driving the AHR in the TME." (PMID 33396563, 2020). "The AhR-dependent signal transduction pathway is known to include the inhibition of apoptosis in cancer cells." (PMID 32325928, 2020). "A multivariate Cox analysis revealed that the strong expression of AhR in cancer cells was a significant and independent predictor of disease-specific survival." (PMID 32443455, 2020). "In this study, we provide evidence that the IDO/TDO-downstream AHR activation represents a common feature of cancers overexpressing IDO or TDO, which dictates a T cell suppressive TME through the establishment of a Treg-macrophage suppressive axis." (PMID 32782249, 2020). "The presence of AhR in the infiltrating cancer cells and the knowledge that SLUG is one of the target gene of AhR, prompted us to investigate the effect of kynurenine in EMT." (PMID 31936153, 2020).
cancer (continued). "AhR affects various types of immune cells and is capable of inducing immunosuppression, and some types of cancer avoid recognition by immune cells via this mechanism." (PMID 32325928, 2020). "As AhR activation suppresses the anti-cancer effects of CD8+ T cells, NK cells, and γδ-T cells, it is notable that African Americans have an elevated risk of an array of different cancers as well as poorer cancer outcomes." (PMID 32867244, 2020). "KYN-101 shares pharmacological properties with the AHR antagonist selected for clinical development in cancer patients." (PMID 32782249, 2020). "The objective of this review is to discuss how the AHR has gone from a likely contributor to genotoxic environmental carcinogen-induced cancer to a master regulator of malignant cell progression and cancer aggression." (PMID 33396563, 2020). "Intracellular retention of the benzothiazoles in the benzothiazole-sensitive carcinoma cells is made possible by cytosolic AhR, leading to AhR-signal transduction activation." (PMID 32443455, 2020). "Regarding the drug transporter regulation, it is known that efflux transporters ABCG2 (BCRP) and ABCB1 (P-gp) are induced by TCDD mediated AhR activation in Caco-2 and other human carcinoma cells including HepG2, LS180, LS174T and MCF7 cells." (PMID 33551819, 2020). "Dioxin and other aryl-hydrocarbon receptor (AhR) agonists (e.g., benzo(a)pyrene and 3-methylcholanthrene [3MC]) can enhance the progression of various cancers, including liver, skin, lung, and renal cancers." (PMID 30872677, 2019). "For example, metformin, a widely used anti-diabetic drug that also has anti-cancer effects, has been shown to inhibit IgE and aryl hydrocarbon receptor-mediated mast cell activation in vitro and in vivo." (PMID 31429774, 2019). "We reported that cancer cells expressed both AhR and PD-L1 at a relatively high level, which represent the main cells on which AhR and PD-L1 were co-localized (arrow)." (PMID 30850589, 2019). "Previous studies have shown that AHR interacts with diverse growth factor transduction pathways in cancer cells." (PMID 31370872, 2019). "Currently, effects of prolonged AhR activation by IDO inhibitors on cancer progression are hard to predict." (PMID 31417567, 2019). "Given the requirement for ligand binding to AHR for its translocation to the nucleus, this nuclear localization of AHR likely reflects an increase in intracellular ligands of AHR in cancer cells." (PMID 31416966, 2019). "In particular, it has been demonstrated that certain AHR ligands stimulate rapid kinase activation, gene expression changes and growth effects in cancer cells through a cross-talk between AHR and EGFR/ERK-mediated signaling." (PMID 31370872, 2019). "Taken together, these findings indicate that AhR plays an important role in the invasiveness of cancer cells and can serve as a prognostic biomarker and potential therapeutic target for patients with urinary system-associated cancers." (PMID 31488157, 2019). "Similar to our data, studies have shown increased levels of AhR in different carcinomas to correlate with poor prognosis." (PMID 31212758, 2019). "CYP1A1 synthesizes the pro-metastatic arachidonic acid metabolite 12(S)-HETE and is induced, e.g., by the activated aryl hydrocarbon receptor, the expression of which is high in many cancer entities and also in MDA-MB231 cells." (PMID 29593542, 2018). "Here, we demonstrate that aryl hydrocarbon receptor (AhR) plays a vital role in the maintenance of cancer stem-like properties." (PMID 29706625, 2018). "AhR promotes the cancer stem-like phenotype and drives metastasis by directly targeting the promoters of ‘stemness’ genes, such as the ATP-binding cassette sub-family G member 2 (ABCG2) gene." (PMID 29706625, 2018). "While still in their infancy, studies of the effects on indoximod and the IDO/TDO/AHR pathways on gut microbial physiology and cancer immunity is a rich area for exploration." (PMID 30254983, 2018).